IL6 (interleukin 6)
Diseases named in the same sentence as IL6 in open-access papers (continued):
Sharing a sentence is not in itself a finding about the gene and the disease.
depression (continued). "We predicted that if IL-6 were related to depression/psychosis risk causally, rather than due to confounding, Asp358Ala would be associated with risk of these disorders, serum IL-6, CRP levels, but not with any of the confounders." (PMID 29197507, 2018). "Previously reported associations between IL-6, depression and psychosis are unlikely to be fully explained by confounders commonly linked with inflammation, depression or psychosis." (PMID 29197507, 2018). "IL-6 is an important marker of leukoaraiosis and contributes to silent cerebral infarction which could result in dementia and depression." (PMID 30096932, 2018). "Major depression patients have abnormal levels of IL-6 and TNF-α, and increased Hp." (PMID 30360353, 2018). "This would also indicate that previously reported associations between IL-6, depression and psychosis are unlikely to be fully explained by confounding (see discussion)." (PMID 29197507, 2018). "A previous study has indicated that IL-6 in hippocampus could induce depression-like behavior in the forced swim test." (PMID 29896129, 2018). "While higher levels of the systemic inflammatory marker IL-6 in childhood are associated with an increased risk of developing depression and psychosis in young adulthood, the results were non-significant for CRP." (PMID 30190688, 2018). "Whether these changes are the direct effect of DHCA or secondary to IL-6 induction, and their potential contribution to attenuate stress-induced depression need further investigation." (PMID 29396460, 2018). "Based on findings from previous studies, we hypothesized that Asp358Ala would be associated with elevated serum IL-6 but decreased serum CRP levels at age 9 years, and with decreased risks of depression and psychosis at age 18 years in the ALSPAC birth cohort." (PMID 29197507, 2018). "Thus, the number of episodes was significantly associated with increasing levels of TNFα and IL-1, while greater increases in serum sIL-1RA and IL-6 were established in puerperal women who had suffered from a lifetime depression." (PMID 29103192, 2018). "IL-6 is a proinflammatory cytokine and the mechanism(s) by which peripheral IL-6 may modulate depression phenotypes are under intense investigation." (PMID 29396460, 2018). "Guiding psychiatric treatment using inflammatory biomarkers such as IL-6, and IL-8 may lead to selection of better drugs to treat each patient’s specific pathophysiological disruptions that contribute to their depression or anxiety." (PMID 29668764, 2018). "However, considering a systematic review on IL-6 and depression, the number of participants in the present study appeared to be too small to examine the IL-6 differences between the two groups." (PMID 30400354, 2018). "Furthermore, besides its direct effect on cancer progression, IL-6 is also related to behavioral side effects of breast cancer such as fatigue, depression, and cognitive disturbances." (PMID 30546293, 2018). "Depression-like behaviour is observed in mice following experimental immune-activation with injection of lipopolysaccharide in peripheral circulation or direct intracerebroventricular injection of IL-6." (PMID 29197507, 2018). "We propose a proof-of-concept, randomised, parallel-group, double-blind, placebo controlled clinical trial to investigate whether IL-6 contributes to pathogenesis of depression and to examine potential mechanisms by which IL-6 affects mood and cognition." (PMID 30244217, 2018). "The findings provide further evidence that the IL-6/IL6R pathways are involved in pathogenesis of severe depression and psychosis, and may be novel therapeutic targets." (PMID 29197507, 2018). "Therefore, the concentrations of cytokines, including IL-1α, IL-1β, and IL-6, were detected by ELISA kits in the serum of mice with restraint stress-induced anxiety and depression." (PMID 30400578, 2018).
depression (continued). "Previously reported associations between IL-6, depression and psychosis are unlikely to be fully explained by confounding." (PMID 29197507, 2018). "IL-6, sIL-6R and hsCRP were found to be increased in euthymia and mania, but not in bipolar depression (for sIL-6R insufficient studies were available to conduct a meta-analysis for depression)." (PMID 30113291, 2018). "Therapy with tocilizumab, a monoclonal antibody against the IL-6 receptor, showed improvement in fatigue symptomatology among patients with rheumatoid arthritis, a disorder strongly related to depression, which positions IL-6 as a therapeutic target of depression." (PMID 30662368, 2018). "Moreover, in the RSDS model, leukocyte-derived IL-6 regulates susceptibility versus resilience to stress, emphasizing the key role of peripheral IL-6 in depression." (PMID 29861834, 2018). "This context provides evidence of how high concentrations of IL-6 may contribute to the onset and development of depression." (PMID 30662368, 2018). "We propose that inhibition of IL-6 signalling in individuals with depression who show evidence of low-grade inflammation and poor response to antidepressants would attenuate their depressive symptoms particularly somatic symptoms of depression." (PMID 30244217, 2018). "Experimental, clinical and epidemiological studies indicate that inflammatory cytokines may contribute to pathogenesis of depression and psychosis, of which interleukin 6 (IL-6) is one of the leading candidates." (PMID 29197507, 2018). "Higher pre-treatment levels of IL-6 predict a poorer response to antidepressants and antipsychotics in patients with depression and schizophrenia, respectively." (PMID 29544672, 2018). "Furthermore, in chronic mild stress (CMS) model of depression, the concentrations of IL-1β, IL-6, IL-18 and TNF-a in the brain or serum were enhanced." (PMID 30390665, 2018). "However, to our knowledge, no interventional study has examined the effects of reducing IL-6 activity on somatic symptoms specifically in individuals with depression." (PMID 30244217, 2018). "The proinflammatory cytokine interleukin (IL)-6 is increased in depression and COPD." (PMID 29854031, 2018). "After Bonferroni adjustment, only IL-6 remained significantly higher in depression." (PMID 30104698, 2018). "Observational studies indicate a potentially causal role for interleukin 6 (IL-6), a proinflammatory cytokine, in pathogenesis of depression, but interventional studies based on patients with depression have not been conducted." (PMID 30244217, 2018). "Several of these cytokines have been linked to depression, such as TNF-alpha and IL-6." (PMID 30148175, 2018). "The main objectives of this study are to test whether IL-6 contributes to the pathogenesis of depression and to examine potential mechanisms by which IL-6 affects mood and cognition." (PMID 30244217, 2018). "This supports other studies that have suggested a role for IL-6 in depression." (PMID 30148175, 2018). "In addition, many studies have also reported increased TNF-α and IL-6 levels in acute phases of mania and depression compared to the controls." (PMID 30170608, 2018). "Both possibilities may explain the recently reported inverse relationship of telomere length with oxidative stress and levels of IL-6 (a component of SASP) in subjects with depression." (PMID 29486769, 2018). "In addition, IL-6 knockout mice showed resilience to stress-induced development of depression-like behaviors, suggesting the role of IL-6 in depression." (PMID 28556833, 2017). "IL-6 may represent a useful biomarker for stress induced depression and anxiety disorders, and manipulations of this cytokine could have potent preventative or ameliorative effects." (PMID 28753980, 2017).
depression (continued). "This study presents evidence that IL6 methylation may be a marker of depression status in older individuals, however further work is now needed to replicate these findings and to assess the association with inflammatory status of individuals." (PMID 29070016, 2017). "Therefore, new chronic diseases are likely to affect patients with depression due to poor self-management as well as the presence of biological inflammatory mediators, such as IL-6 and C-reactive protein (CRP)." (PMID 29070021, 2017). "It is possible that IL6 methylation is reflective or results from processes occurring with depression, it could influence cytokine levels themselves and thus directly influence depression risk, or it could be a marker of a common aetiology." (PMID 29070016, 2017). "Patients with major depression have increased Interleukin 6 (IL-6)." (PMID 30886949, 2017). "In addition, elevated circulating IL-6 has been reported in several animal models of depression in which chronic mild stress or learned helplessness was applied to establish depressive-like symptoms." (PMID 29176954, 2017). "Moreover, the assessment of clock gene expression in the hippocampus, a brain region involved in AD and depression, revealed altered levels of cry1, dec2, and rev-erb-beta in IL-6 KO mice." (PMID 28382017, 2017). "Interestingly, higher serum levels of IL-1β and IL-6 in the rat with depression-like phenotype were normalized after a single dose of ketamine." (PMID 28600519, 2017). "Indeed, it has been suggested that social interaction reduces post-stroke depression and improves functional recovery by down-regulating hippocampal IL-6 level in an animal model of stroke." (PMID 29137271, 2017). "Indeed, BDNF and IL6 appear to have opposing roles in depression - BDNF is thought to interact negatively with inflammatory processes in the brain and there is attenuation of BDNF availability with increased inflammation." (PMID 29070016, 2017). "Significantly higher concentrations of TNF-α and IL-6 in depressed subjects compared with control subjects have also been determined by means of a large meta-analysis of studies measuring cytokine concentration in patients with major depression." (PMID 29109914, 2017). "Although we did not measure cerebrospinal fluid (or brain) levels of IL-6 in susceptible mice after intracerebroventricular infusion of MR16-1, it is unlikely that brain IL-6 may have a key role in depression-like phenotypes in rodents." (PMID 28556833, 2017). "In addition, this is also the first study showing the role of serum IL-1β and IL-6 in the individual differences of ketamine’s antidepressant response in the comorbidity of neuropahtic pain and depression in rodents." (PMID 28600519, 2017). "Another study found that XPJY has the better effect on improving learning and memory ability in depression rats than sertraline, which might he related to reduce the inflammatory factors level, such as IL-1β, IL-6 and TNF-α, in serum and hippocampus." (PMID 28118829, 2017). "However, IL-6 is usually found to be elevated in plasma of depressed patients especially in treatment-resistant major depression." (PMID 29317891, 2017). "Considering the key role of IL-6 in depression, the present study investigated whether anti-mouse IL-6 receptor antibody (MR16-1) induces antidepressant-like effects in the social defeat stress model." (PMID 28556833, 2017). "Our earlier studies have shown that learning and memory ability in depression rats might be related to reduce the inflammatory factors level, such as IL-1β, IL-6 and TNF-α, in serum and hippocampus." (PMID 28118829, 2017). "Moreover, there are findings, suggesting that increased secretion of IL-6 is involved in the pathogenesis of depression." (PMID 26649857, 2017). "Meta-analyses indicate raised levels of IL-6 in groups of patients with major depression." (PMID 27503474, 2016). "Elevated plasma proinflammatory IL-6 levels were reported in patients with major depression." (PMID 28074100, 2016).
depression (continued). "Therefore, it is plausible that the associations of hopelessness with IL-6 and CRP and of depression with CRP and MMP-9, all of which vanished after adjustment for physical and lifestyle factors, are mainly reliant on lifestyle factors." (PMID 26979423, 2016). "Thus, painful conditions might be able to induce depression in CG heterozygotes, where the expression rate just slightly changed, while only homozygous CC carrier status causes vulnerability to other life stressors, where the IL-6 expression rates changes more considerably." (PMID 26821321, 2016). "However, based on the available literature and our results, IL-6 seems to have a two-faced effect on depression phenotype." (PMID 26821321, 2016). "Moreover, stress response and depression involve secretion of interlukin-6 (IL-6), a pleiotropic, inflammatory cytokine that is also involved in t umour angiogenesis and invasion." (PMID 27036549, 2016). "Based on the previous studies which investigated plasma IL-6 levels in depression and during stressful experiences we can assume that our risk variant, namely the C allele, might induce over expression of IL-6 and thus increase depressive symptom scores." (PMID 26821321, 2016). "As modulators of IL-6 have been suggested to have a therapeutic potential for treatment-resistant depression, further investigation of let-7 is indicated to test this hypothesis." (PMID 27529677, 2016). "Only depression scores (Ptrend = 0.0004) and mean arterial pressure (Ptrend = 0.015) were found to be linearly independent predictors for fatigue, controlling for age, Il-6 levels, and body mass index." (PMID 27148509, 2016). "Finally, as basal levels of CRP, IL-6 and TNF-α areavailable, we are able to compare associations of basal versus LPS-stimulatedcytokine levels with depression and anxiety within the same study sample (fourthaim)." (PMID 27244234, 2016). "Again, a reduction of serum IL-6 levels correlated very well with a reduction in depression score." (PMID 28082989, 2016). "Additionally, further studies need to be conducted examining IL-6 mRNA levels in participants with schizophrenia when compared to other psychiatric disorders, specifically depression." (PMID 27206977, 2016). "Of particular interest in depressive disorders are the cytokines IL-β, IL-6, and TNF-α." (PMID 26775294, 2016). "A correlation analysis of the Hospital Anxiety and Depression Scale score and cytokine levels revealed positive associations with the domain of anxiety/depression with IL-6, IL-1beta and TNF-alpha and a negative correlation with IL-10." (PMID 26300773, 2015). "As hypothesized, interactive effects were revealed at loci in IL6 and IL1β that accounted for differences in depressive symptoms, over and above the contributions of maternal depression history, earlier depressive symptoms, gender, and asthma diagnosis." (PMID 25596176, 2015). "Here we tested the hypothesis that IL6-induced modulation of serotonergic neurotransmission through the STAT3 signaling pathway contributes to the role of IL6 in depression." (PMID 25760924, 2015). "Linear regression was used to determine whether allelic variation at IL6 might moderate the impact of stress exposure on age 20 depression severity, over and above the effects of the covariates." (PMID 25596176, 2015). "Higher concentrations of IL-6 as well as increased gene-activity are established bio-markers for depression, yet, less is known about the inflammatory mechanisms that result from the interaction of insomnia and depression, and the resolution of symptoms." (PMID 25983695, 2015). "Similar to the current results, in animal models of sickness behavior, prolonged production of TNF-α, IL-6, and IL-1β can also lead to a variety of symptoms including fat and muscle wasting and behavioral changes similar to symptoms of depression that also occur in cancer patients." (PMID 25945105, 2015).
depression (continued). "There are some studies indicating that depression may be associated with elevated levels of IL-1β, TNF, and IL-6." (PMID 26624891, 2015). "Furthermore, baseline CRP and IL-6 measurements have been observed to effectively predict future depression at 12-year follow-up, while baseline symptoms of depression were not predictive of future inflammatory markers." (PMID 26550011, 2015). "Our result showed there was significant correlation between depression and serum IL-6 level." (PMID 25922648, 2015). "The mean IL6 was significantly higher in those with depression symptoms." (PMID 26040277, 2015). "Improving both NGF and IL-6 secretion can be important during neonatal development, in control of “adult” neurogenesis in the hippocampus and neocortex and also in the pathogenesis of diseases such as Alzheimer’s disease, Parkinson’s disease, or depression." (PMID 25841889, 2015). "IL-6 also crosses the blood–brain barrier and contributes to central inflammation, and higher activity can contribute to mood alterations including symptoms of depression and anxiety." (PMID 25983695, 2015). "Finally, there has been an inverse relationship between plasma IL-6 level and verbal memory in patients with depression." (PMID 25214388, 2015). "In addition, the elevated levels of pro-inflammatory cytokines (e.g., IL-6 and IL-1β) can induce symptoms of a syndrome termed “sickness behavior”, which include depression, reduction in locomotor activity, anhedonia, anorexia and cognitive disturbances." (PMID 25514226, 2014). "Depression is associated with an innate inflammatory response, and a meta-analysis by Howren and colleagues has shown depressive symptoms to be positively associated with CRP, IL-1 and IL-6 in both clinical and community samples." (PMID 24239712, 2014). "Activation of mast cells following neurological diseases such as depression, through release of mediators such as eicosanoids, serotonin, and IL-6, could contribute to the pathogenesis of IBD." (PMID 27355055, 2014). "Correlation analysis between HADS score and cytokine levels revealed a positive association of anxiety and/or depression with IL-1β, IL-6, IL-8, and TNF-α and a negative correlation with IL-10." (PMID 25309921, 2014). "IL-6 increases hippocampal IDO expression levels with depressive-like behavior in FST, suggesting that amino acid metabolism is possibly linked with inflammation-induced comorbid depression." (PMID 25309465, 2014). "Recent clinical work reports on elevated IL-6 and decreased IL-10 in depression." (PMID 23520517, 2013). "However, previous studies have reached divergent conclusions about the relationship between depression and the levels of IL-6." (PMID 23497121, 2013). "The combined role of IL-6 and IL-10 in depression have garnered recent attention with the recognition of human populations suffering from major depression displaying commensurate increases in IL-6 and decreases in IL-10, providing direct biological correlation with this animal model." (PMID 23520517, 2013). "In addition, preliminary findings suggest a relationship between depression, markers of inflammation (such as IL-6 and CRP), and telomere length." (PMID 23691300, 2013). "Meta-analysis confirmed the association between IL-6, CRP and IL-1β levels and depression." (PMID 24244750, 2013). "Activated microglia employ IL-6 and TNF-α as antineurogenic signals, which can interact directly with neural progenitor cells via TNF and IL-6 receptors causing a decrease in neurogenesis, and also in emotion-regulating brain structures involved in depression." (PMID 23672628, 2013). "One of the best studied cytokines in depression is interleukin (IL)-6 for which increased concentrations could be confirmed meta-analytically." (PMID 23951008, 2013).